IL6 (interleukin 6)
Diseases named in the same sentence as IL6 in open-access papers (continued):
Sharing a sentence is not in itself a finding about the gene and the disease.
depression (continued). "Chronic stress accelerates dementia onset in depression via cytokines, with elevated interleukin-6 and tumor necrosis factor-α levels observed in the serum, cerebrospinal fluid, and prefrontal cortices of depressed patients." (PMID 39981405, 2025). "This reduction is particularly beneficial for individuals with chronic stress and depression, as elevated IL-6 levels are common in these conditions." (PMID 41262963, 2025). "included 34 related studies in a meta-analysis and reported that the level of IL-6 in peripheral blood was significantly increased in elderly people with depression; thus, elderly patients should be monitored for excessive IL-6 levels during daily management." (PMID 40405880, 2025). "Among them, high plasma levels of IL-6 are related to accelerated tumor progression, high-stress states, depression, and abnormal behavior." (PMID 40966684, 2025). "(2020) analyzed serum levels of IL-6 and IL-8 in 40 patients with major depression (mean age ± SD: 41.8 ± 13.7; 55% female) treated with ECT." (PMID 40969698, 2025). "Pro-inflammatory cytokines that are involved in the pathogenesis of RA and PsA, including TNF-α, IL-1 and IL-6, are also elevated in patients with a depression or anxiety disorder." (PMID 39504461, 2025). "According to network pharmacology results, IL-6, IL-1β, TNF-α, and IL-10 are closely associated with SD and depression." (PMID 40076470, 2025). "Elevated levels of pro-inflammatory cytokines such as IL-6 and TNF-α have been associated with depression, fatigue, and cognitive impairment, which are frequently reported in pSS." (PMID 40530052, 2025). "Emerging studies further highlight a close association between the development and progression of depression and the involvement of key proinflammatory cytokines IL-1β, TNF-α, and IL-6." (PMID 40710585, 2025). "Multiple studies have demonstrated that individuals with depression exhibit elevated proinflammatory cytokines, such as interleukin-6 (IL-6), tumor necrosis factor-α (TNF-α), and C-reactive protein (CRP), and decreased anti-inflammatory mediators." (PMID 41541965, 2025). "Inflammatory blood biomarkers such as IL-6, PCR, and HsCRP are related to depression and anxiety and used to detect multiple diseases." (PMID 40563433, 2025). "Assessments have indicated that hypermethylation of BDNF and NR3C1 is associated with an increased risk of depression, while the methylation profiles of DNMT1/3A, EZH2, and IL-6 correlate to the severity of anxiety." (PMID 39851502, 2025). "Instead, depression showed a different neuroinflammatory response with lower IL-1β and higher IL-6 and IL-10 expression compared to the controls." (PMID 40179065, 2025). "The degree of psychopathological changes in patients with schizophrenia or depression was linked with the levels of the following pro-inflammatory cytokines: IFN-α, IFN-γ, IL-1β, IL-6, and TNF-α." (PMID 41010622, 2025). "Compared with healthy individuals, patients with depression exhibit significantly higher serum/plasma levels of pro-inflammatory cytokines such as IL-6 and C-reactive protein (CRP)." (PMID 39980978, 2025). "Depression trajectories and mean depressive scores across all IL-6 tertiles were worse in females compared to males." (PMID 39865800, 2025). "Clinical validation of this axis is underscored by robust correlations between serum IL-6 levels and Hamilton Depression Rating Scale scores in IBD cohorts." (PMID 40909294, 2025). "Elevated levels of proinflammatory cytokines, such as interleukin-6 (IL-6), tumor necrosis factor-alpha (TNF-α), and C-reactive protein (CRP), have been observed in subsets of patients with depression and have been associated with poor treatment outcomes." (PMID 41155383, 2025). "A mechanistic RCT showed that a four-week, multi-strain probiotic not only reduced Hamilton Depression Rating Scale scores but also dampened plasma IL-6 and normalised functional connectivity within reward networks." (PMID 41373485, 2025).
depression (continued). "Large-scale research in adults, using UK Biobank data, observed a causal relationship between both inflammatory markers, CRP and IL-6, and depression." (PMID 40823322, 2025). "In the female group, the highest interaction intensities (%) for depression were observed with IL-6, hsCRP, CRP, vitamin D, and D-dimer." (PMID 40563433, 2025). "Similar relationships were observed between IL-6 and depression trajectories in two different cohorts despite their heterogeneity and no overlap in ages." (PMID 39865800, 2025). "A hallmark of depression is a heightened level of pro-inflammatory cytokines, including Tumor Necrosis Factor-α (TNF-α), Interleukin-6 (IL-6), and Interleukin-1β (IL-1β)." (PMID 41480347, 2025). "IL-6, for example, is elevated in microglia following EphB2 treatment but also in the brains of PLWH and is associated with HIV induced depression." (PMID 40588746, 2025). "Future studies should combine biomarkers (e.g. IL-6, CRP) and psychosocial variables to uncover the multilevel mechanisms underlying the somatization-depression relationship." (PMID 40236492, 2025). "Phenome-wide analyses replicated these findings and supported repurposing opportunities for IL-6 inhibition toward depression and gallstone disease." (PMID 40858837, 2025). "As far as we are aware, only two studies and one review reported on the influence of BLT on peripheral, i.e., plasma IL-6 levels in individuals diagnosed with depression." (PMID 40001598, 2025). "In animal models of depression, early-life stress significantly increased the expression levels of IL-1β, IL-6, and TNF-α in the brain, while blood levels remained unchanged." (PMID 41301474, 2025). "Chronic social stress reduces tight-junction protein claudin-5, breaches the BBB, and enables peripheral IL-6 infiltration into limbic circuits, driving depression-like behaviors; convergent work confirms stress-induced BBB pathology across models." (PMID 41244880, 2025). "It amplifies chronic inflammation by stimulating T- and B-cells; therefore, high concentrations of IL-6 suggest a relation between depression and COPD." (PMID 40724725, 2025). "For instance, raised levels of CRP (>3 mg/L) in patients with depression, together with elevated levels of IL-6 and other inflammatory cytokines in blood and cerebrospinal fluid in patients with depression, are indicators of low-grade systemic inflammation." (PMID 38545720, 2025). "Elevated levels of IL-6 have been documented in patients with depression and this cytokine is known to influence the HPA axis, which plays a significant role in the stress response and mood regulation." (PMID 40305200, 2025). "There was also strong evidence of the sex-specific effects of IL-6 on depression trajectories in ALSPAC and weaker evidence in the UK Biobank." (PMID 39865800, 2025). "Evidence suggested a potential link between cancer‐induced stress and depression, with increased levels of proinflammatory cytokines (such as IL‐6) and dysregulation of neurotransmitters, including serotonin, contributing to the onset of depression." (PMID 40387308, 2025). "The results revealed sex-specific differences in biomarker relevance, with vitamin D, CRP, and D-dimer being the most predictive for depression in men, while IL-6, CRP, and vitamin D were significant in women." (PMID 40563433, 2025). "Elevated interleukin (IL)-6 plasma concentrations were measured in elderly patients with major depression." (PMID 40509339, 2025). "Elevated proinflammatory cytokines like IL‐6 and TNF‐α are associated with depression in cancer patients." (PMID 40387308, 2025). "Patients with depression exhibit elevated levels of pro-inflammatory cytokines (IL-6, IL-8), interferon-gamma (IFN-γ), and TNF-α." (PMID 40699781, 2025). "In patients with cancer as well as depression and fatigue, there are also elevated circulating inflammatory cytokines, and peripheral blood interleukin (IL)-1β, IL-6, tumor necrosis factor, and CRP levels show an increasing trend." (PMID 40966684, 2025).
depression (continued). "Meta-analyses indicated an increase of inflammatory biomarkers such as IL-6, IL-18 in depression but regarding TNF-α there were inconsistent reports." (PMID 39717874, 2025). "Variations in immune response genes like IL6 and TNF are linked to treatment-resistant epilepsy and depression, indicating common neuroinflammatory mechanisms." (PMID 40941042, 2025). "Among all tested parameters only IL-6 came out as an independent predictor for depression while ESSPRI fatigue was an independent predictor for anxiety in pSS." (PMID 40822847, 2025). "Previous studies have reported that microglia in the brains of depression patients exhibit abnormal activation, with significantly elevated expression levels of pro-inflammatory cytokines IL-1β, IL-6, and TNF-α." (PMID 41244868, 2025). "Physiologically, chronic social isolation has been linked to dysregulation of the hypothalamic-pituitary-adrenal (HPA) axis and elevated inflammatory markers (e.g., IL-6, CRP), which are implicated in depression." (PMID 40462874, 2025). "Choy and Calabrese described the role of IL-6 in the development of pain and weakness in patients with RA and studied its role in patients with depression." (PMID 40699818, 2025). "The primary outcomes were changes in Hamilton Depression Rating Scale (Ham-D) scores and serum IL-6 concentrations." (PMID 41057811, 2025). "Saikosaponin C ameliorates CSDS-induced depression-like behaviors by inhibiting DNA methyltransferase 1, thereby decreasing IL-6 methylation and expression, while enhancing synaptic plasticity." (PMID 40936908, 2025). "In this model, compared to the control cells, the levels of 5‐HT and GABA were significantly lower, while TNF‐α, IL‐1β, and IL‐6 levels were markedly higher in the CORT‐induced depression cell model." (PMID 40491976, 2025). "Although the exact mechanism of pathogenesis is not known, a large number of studies have observed a connection between concentration of IL-6 and depression." (PMID 40822847, 2025). "IL-6, a multifunctional inflammatory molecule, shows increased levels in patients with both treatment-resistant epilepsy and major depression, where it promotes disease progression through several pathways." (PMID 40941042, 2025). "Patients with either depression or anxiety had significantly higher IL-6 concentration (P < 0.001 and P = 0.002, respectively)." (PMID 40822847, 2025). "Elevated levels of pro-inflammatory cytokines, such as interleukin-6 (IL-6) and tumor necrosis factor-alpha (TNF-α), have been associated with impaired cognitive control and increased risk of depression and anxiety." (PMID 40062198, 2025). "The most recent studies have shown an increased concentration of IL-6 in the blood of patients with depression and a positive correlation between the concentration of cytokines in the cerebrospinal fluid with disease activity in depressed patients." (PMID 40822847, 2025). "The pro‐inflammatory factors such as TNF‐α, IL‐1β, and IL‐6 are classical markers of inflammation frequently studied in the context of depression." (PMID 40491976, 2025). "Consistent with other studies investigating peripheral inflammation, our study showed an increase of IL-6 in depression brains." (PMID 40179065, 2025). "Inflammation, marked by elevated levels of cytokines such as interleukin-6 (IL-6) and tumor necrosis factor-alpha (TNF-α), has been directly associated with depression, suggesting an inflammatory component to the disorder." (PMID 39911326, 2025). "A key marker of inflammation in depression is interleukin-6 (IL-6), a proinflammatory cytokine involved in the transition from acute to chronic low-grade inflammation." (PMID 41210298, 2025). "Our study has demonstrated a positive association between cytokines TNF-α and IL-6 and the degree of depression in patients with rheumatoid arthritis, as well as between IL-6 levels and disease activity measured by rheumatoid arthritis activity indexes." (PMID 40699818, 2025).
depression (continued). "The aim of our study was to explore the correlation between cytokines TNF-α and IL-6, disease activity, and the degree of depression in patients with RA." (PMID 40699818, 2025). "In contrast, the male group showed significant results only in individuals with moderate depression, with key correlations observed between Myo and D-dimer, CK-MB and cTnI, cortisol and IL-6, and vitamin D and hsCRP." (PMID 40563433, 2025). "Nigella sativa oil (100 mg/kg, 10 weeks) decreased IL-6, reduced body weight by 18%, and improved mood scores in obese rats with depression." (PMID 40649341, 2025). "Patients with depression often exhibit an increase in T helper 17 (Th17) cells and a decrease in Tregs, with inflammatory cytokines like IL-6 promoting Th17 differentiation while inhibiting Treg development." (PMID 40641625, 2025). "Inflammatory markers (C-reactive protein (CRP) or interleukin-6 (IL-6)) can predict future depression." (PMID 40821024, 2025). "Neuroinflammation has emerged as a core feature of many psychiatric disorders, particularly schizophrenia and depression, where pro-inflammatory cytokines such as IL-6, TNF-alpha, and C-reactive protein are persistently elevated." (PMID 40218925, 2025). "CRP, C-reactive protein; GDS, Geriatric Depression Scale; IL-6, interleukin 6; IL-18, interleukin-18; MMSE, Mini Mental State Examination; NSAIDS, non-steroidal anti-inflammatory drugs." (PMID 41419753, 2025). "For example, the difference in the amount of IL-6 in the group with depression was 90-fold greater than in controls (978.1 pg/mL versus 11.1 pg/mL)." (PMID 40141399, 2025). "In adults with depression, elevated levels of IL-6 and, to a lesser extent, TNF-α and C-reactive protein (CRP) have been consistently reported." (PMID 40563330, 2025). "Pro-inflammatory cytokine levels, including TNF-α, IL-6, and IL-1β, are continuously elevated in patients with AD, MS, and depression." (PMID 39861166, 2025). "Only IL-6 was identified as an independent predictor of depression (OR = 3.45, 95%CI: 1.12-10.62, P = 0.031)." (PMID 40822847, 2025). "Stress increases inflammatory cytokines (TNF-α, IL-1β, and IL-6), which disrupt neurotransmitter levels (serotonin, dopamine, and norepinephrine), contributing to disorders such as anxiety, depression, and neuroinflammation." (PMID 40309824, 2025). "Microglial activation and the subsequent release of inflammatory factors (TNF-α and IL-6) are key contributors to anxiety and depression-like phenotypes." (PMID 41465379, 2025). "Inflammatory cytokines like IL-1, IL-2, and IL-6 have been shown to predict treatment outcomes in treatment-resistant depression." (PMID 40370590, 2025). "Estrogen also modulates inflammatory pathways, with low estrogen states associated with elevated pro-inflammatory cytokines (e.g., IL-6, TNF-α), which are implicated in depression." (PMID 40412096, 2025). "Studies have consistently found that individuals with depression often exhibit elevated levels of inflammatory markers in their blood and cerebrospinal fluid, including cytokines such as IL-1β, IL-6, and TNF." (PMID 40065395, 2025). "In a Mendelian randomization study involving candidate genes, a functional SNP in the IL-6 receptor promoter was identified, providing estimates of CRP, IL-6, and the severity of depression symptoms in a population cohort study." (PMID 40807142, 2025). "Enhanced levels of neuroinflammatory cytokines (such as IL-1β, TNF-α, and IL-6) are observed in individuals with depression." (PMID 40703750, 2025). "Results show that patients with depression had significantly higher increases at 2 years compared to baseline for all investigated parameters (CRP—p = 0.001/Fibrinogen—p < 0.001/Interleukin-6—p < 0.001/TNF-α -p < 0.001/Cortisol—p < 0.001)." (PMID 40363978, 2025). "Of the data available, two studies found higher inflammatory protein concentrations in individuals with MS and depression for IL-6 and sIL6R." (PMID 39867847, 2025).
depression (continued). "Anxiety and depression are linked to increased levels of pro-inflammatory cytokines such as TNF-α and IL-6." (PMID 41462928, 2025). "It is also important to note the correlation between IL-6 and the development of depression in other physical diseases, including breast cancer, ovarian cancer, metastatic cancer, colorectal cancer, cardiovascular disease and rheumatological diseases." (PMID 41463013, 2025). "On the one hand, increased IL-6 synthesis is observed in RA, which leads to increased inflammation of the joints and significantly contributes to the development of depression." (PMID 41464826, 2025). "In the depression group, increase of IL-6 and IL-10, and decrease of IL-1β were observed compared to controls, with no changes detected for the other cytokines and the endothelial markers." (PMID 40179065, 2025). "Clinical trials have demonstrated its potential to reduce levels of interleukin-6 (IL-6), enhance the activity of the antioxidant enzyme GPx, and alleviate symptoms such as anxiety and depression in patients with PCC." (PMID 40722944, 2025). "Increased levels of inflammatory mediators, such as cytokines like IL-1β, TNF-α, and IL-6, are often seen in patients who suffer from severe depression." (PMID 40574754, 2025). "Inflammatory responses, characterized by elevated levels of proinflammatory cytokines such as interleukin‐6 (IL‐6) and tumor necrosis factor‐alpha (TNF‐α), have been implicated in the development of depression in cancer patients." (PMID 40387308, 2025). "For instance, mutations in the interleukin-6 receptor (IL-6R) within the brains of depression patients can lead to the activation of IL-6 trans-signaling pathway, subsequently triggering neuroinflammation and psychiatric disorders." (PMID 40334255, 2025). "Assessments of interleukin 6 (IL‐6) levels, sleep quality, pain catastrophising, affect, and symptoms of depression and anxiety were included in the baseline and follow‐up sessions." (PMID 39289848, 2025). "For depression, IL-6 overstimulates the body’s stress response system, the hypothalamic–pituitary–adrenal (HPA) axis, leading to impaired regulation of stress hormones and prolonged stress responses." (PMID 40941042, 2025). "In terms of the outcome, this study primarily selected IL-1β, IL-6, and TNF-α as inflammatory biomarkers associated with depression." (PMID 41194929, 2025). "Concurrently, patients with depression commonly exhibit chronic low-grade inflammation, characterized by persistently elevated pro-inflammatory cytokines [e.g., interleukin-6 (IL-6), Tumor Necrosis Factor-alpha (TNF-α)] and excessive activation of glial cells." (PMID 40641625, 2025). "Remarkably, IL‐6 knockdown in hippocampal microglia significantly reduced social avoidance, depression‐like behaviors, and anxiety‐like behaviors induced by CSDS without affecting overall motor activity." (PMID 39888279, 2025). "In an in vivo model, tRES-HESP improved memory and depression-like behaviors, reduced cortisol and interleukin (IL)-6 levels, increased IL-10 levels, and lowered the expression of amyloid precursor protein and amyloid beta." (PMID 40362855, 2025). "IL-6 promoter methylation in DNA extracted from buccal swabs was found to be lower in older adults (≥65 years) with major depressive disorder (MDD) compared to healthy controls." (PMID 41179817, 2025). "The pathogenesis of depression is correlated with inflammation, specifically the IL-6/IL-6R pathways; peripheral blood levels of inflammatory markers increased during the acute episodes of depression." (PMID 41274868, 2025). "IL-6 Blockade: Tocilizumab, an IL-6 receptor antagonist, has been studied in relation to depression and schizophrenia." (PMID 39861166, 2025). "Inflammatory cytokines, such as TNF-α and IL-6, are elevated in both inflammation and depression, creating a vicious cycle that exacerbates both physical and mental health." (PMID 40115342, 2025).